TTF1 (transcription termination factor 1)
Diseases named in the same sentence as TTF1 in open-access papers (continued):
Sharing a sentence is not in itself a finding about the gene and the disease.
TTF1 also shares sentences with these, for which no sentence is quoted: papillary carcinoma (6 papers); breast adenocarcinoma (3); endometrial carcinoma (3); paraganglioma (3); adenoid cystic carcinoma (2); endometrioid adenocarcinoma (2); gynecologic cancers (2); kidney cancer (2); lymph node metastasis (2); pancreatic adenocarcinoma (2); pancreatic NETs (2); prostate small cell carcinoma (2); rhabdomyosarcoma (2); salivary gland tumors (2); schwannoma (2); serous carcinoma of the ovary (2); signet-ring cell adenocarcinoma (2); squamous non-small cell lung cancer (2); struma ovarii (2); transitional cell carcinoma (2); acute lung injury (1); angiosarcoma (1); B-cell neoplasm (1); basal cell carcinoma (1); Benign Hereditary Chorea (1); benign thyroid tumor (1); bladder carcinomas (1); bronchioloalveolar carcinoma (1); bronchopneumonia (1); carcinosarcoma (1).
A further 64 diseases each share a sentence with TTF1 in 1 paper.